IDH1 (isocitrate dehydrogenase (NADP(+)) 1)
Diseases named in the same sentence as IDH1 in open-access papers (continued):
Sharing a sentence is not in itself a finding about the gene and the disease.
tumor (continued). "The high mTOR activity related biological advances in tumour proliferation were inhibited by rapamycin both in vitro and in vivo in the studied heterozygous IDH1 mutant cells." (PMID 28578659, 2017). "Taken together, these results suggested that clomifene effectively and safely suppresses the tumor growth in vivo by inhibiting mutant IDH1." (PMID 28498812, 2017). "Mutations in the RTK genes involving EGFR, ERBB2, ERBB4, FLT1 and EPHA/B, were identified in 5/7 (71%) of the H3/IDH1 wildtype tumor pairs." (PMID 29084603, 2017). "In all patients and IDH1-wildtype group, the tumor volume and mean ADC value based of FLAIR images had a significant negative correlation with BCAT1 expression, which was observed independently with IDH1 mutation status." (PMID 29255149, 2017). "One particular case of benign brain was observed to have a small focus of tumor cells that was identified by anti-IDH1 R132H." (PMID 31548536, 2017). "In order to further reveal the relationship between antitumor effects and inhibitions of mutant IDH1 enzymes by clomifene, tumor tissues extracted from different groups were subjected to an immunohistochemistry analysis for H3K9me3." (PMID 28498812, 2017). "In IDH1 mutant tumors, HGG7 harbored two ATRX alterations including a frameshift mutation exclusive to the primary tumor, while HGG6 acquired an additional ATRX missense mutation in the recurrence, in keeping with previous findings in IDH1 mutagenesis." (PMID 29084603, 2017). "Although some researchers suggested that IDH1 and 2 act as tumor suppressor genes, the accumulating evidence disagrees with that." (PMID 28785398, 2017). "IDH1 status was associated with numerically higher plasma macrophage-derived chemokine (MDC/CCL22), higher whole blood FOXP3, and reduced tumor CD3+ T cell counts." (PMID 28481241, 2017). "Treatment with ABT263 resulted in a marked reduction of the tumor growth rate of both HCT116 IDH1 WT- as well as HCT116 IDH1 R132H-expressing tumors." (PMID 29057925, 2017). "In contrast, R132H IDH1 GBM tumours expressing WT β1 integrin had low to negligible HIF1α and TNC protein expression, despite pronounced hypoxia." (PMID 27820599, 2016). "In vivo MRI showed that the increase in both tumor volume and nCBV after bevacizumab treatment in IDH1 WT tumors was significantly higher compared with BCAT1 sh#1tumors." (PMID 27626306, 2016). "Somatic mutations in the isocitrate dehydrogenase 1 (IDH1) or IDH2 genes are common in enchondromas and chondrosarcomas, as well as in several neoplasms, including glioma, glioblastoma, acute myeloid leukemia, and intrahepatic cholangiocarcinomas (IHCC)." (PMID 26920730, 2016). "In both the primary and U87 xenograft models, we noted that the softer IDH1-mutant-expressing GBM tumours had low to negligible TNC expression." (PMID 27820599, 2016). "We found that the expression of IDH1-R132H correlated with GC, indicated by tumor stage, especially lymph node metastasis." (PMID 27655638, 2016). "Analysis of WT and R132H IDH1 GBM xenografts revealed that R132H IDH1 tumours had low to barely detectable nuclear HIF1α (and TNC) despite evident necrosis (asterisks) and hypoxia." (PMID 27820599, 2016). "In this study, we evaluated a representative LGG case in which IDH1-R132H was detected at the center of the tumor concurrent with wild-type IDH1 at the margin." (PMID 27877908, 2016).
tumor (continued). "Tumours derived from R132H IDH1 GBM cells expressing the V737N integrin demonstrated increased mechanosignalling, and expressed elevated levels of both HIF1α and TNC." (PMID 27820599, 2016). "For both the LGG and GBM samples, we noted that the stiffness of the ECM in the R132H IDH1 tumours was significantly less than the ECM measured in the WT IDH1 tumours." (PMID 27820599, 2016). "Immunohistochemistry with the IDH1R132H antibody using the corresponding tumor specimen revealed highly necrotic tissue containing sparsely distributed mutant IDH1-positive tumor cells." (PMID 27529619, 2016). "Indeed, IDH1 mutation results in gain of function to catalyze the production of hydroxyglutarate (2-HG), a possible oncometabolite that is thought to influence a range of cellular programs involved in epigenetic control and various processes leading to tumor development." (PMID 26858939, 2016). "Two studies validated a single-voxel 1H-MR double-echo Point RESolved Spectroscopy (PRESS) sequence to estimate 2-HG levels in mutant IDH1 tumor patients." (PMID 27014635, 2016). "To investigate the role of BCAT1 in tumor cells, we used the IDH1 WT-expressing human U87 MG GBM cell line and stably knocked down BCAT1 using shRNA." (PMID 27626306, 2016). "Tumor volume ratio (log10%) in IDH1 WT was significantly increased after bevacizumab treatment than BCAT1 sh#1 rats (2.3210 [IQR, 2.2505–2.6005] vs 2.1370 [1.9173–2.2232]; p = 0.0181)." (PMID 27626306, 2016). "The three tumor samples classified as proneural were tightly clustered and included two of three IDH1 mutant tumor samples, consistent with other studies demonstrating this strong association." (PMID 26757882, 2016). "PCR and subsequent SS were performed on 192 tumor DNA samples for IDH1 codon R132, and were classified as either seq-mut (n = 79; 77 R132H and 2 R132G) or seq-wt (n = 113)." (PMID 27529619, 2016). "We found that in GC, low expression of IDH1-R132H was correlated with tumor stage (X2=13.1516, P=0.041) and lymph node metastasis (X2=12.4282, P=0.006)." (PMID 27655638, 2016). "In the current study, we compared the expression of IDH1 in the tumor tissue with that in the paracancerous tissue by quantitative real-time PCR (qRT–PCR), immunohistochemistry, and Western blot analysis." (PMID 27863386, 2016). "Though not yet confirmed by clinical trials, at least three preclinical studies have demonstrated a therapeutic effect of DNA hypomethylating agents on IDH1-mutant tumor cell lines." (PMID 27556016, 2016). "Multivariate analysis of OS and PFS included age, KPS, tumor grade, extent of resection, radiotherapy, TMZ chemotherapy, IDH1 mutation and MGMT promoter methylation." (PMID 27590514, 2016). "Recent studies have shown that IDH1 (R132H) represents an immunogenic tumor antigen recognized by CD4+IFN-γ-producing T cells in patients." (PMID 27738332, 2016). "In CRC, the expression of IDH1-R132H was correlated with location, differentiation, tumor stage, lymph node metastasis and distant metastasis." (PMID 27655638, 2016). "In a subgroup of patients with ≥40 % EOR (n = 39), however, initial and residual tumor volumes were prognostic for OS (HR 1.03, p = 0.005 and HR 1.08, p = 0.007, respectively), persistent to adjustment for IDH1." (PMID 27344556, 2016). "Patient characteristics and genetic markers (IDH-1 mutation, MGMT promoter methylation and the subtype genetic signature of the respective tumor samples) were assessed." (PMID 26978262, 2016). "The presence of the H3/H3′ multiplet can be clearly seen in the raw IDH1 tumor spectrum and in a further 6 patients (including the TBC patient) who underwent scanning with semi-LASER." (PMID 27547821, 2016). "By the log rank test, low IDH1-R132H expression (P<0.001), differentiation (P<0.001), and tumor stage (P<0.001) all correlated negatively with OS." (PMID 27655638, 2016).
tumor (continued). "Third, IDH1 mutant tumours were identified by immunohistochemical analysis using an antibody that is specific for the R132H mutation." (PMID 25849605, 2015). "This provides a strong argument that the cartilaginous tumours harbouring the genetically altered IDH1 are good candidates for the selective inhibitors of the metabolic enzyme, IDH1." (PMID 25432631, 2015). "Patients with IDH1-R132H positive tumours were less likely to die within 12 months of the initial diagnosis (17% vs. 47%; p = 0.046)." (PMID 25849605, 2015). "There was a significant association between IDH1 mutations and 5-ALA fluorescence in tumor tissue (p = 0.03)." (PMID 26008980, 2015). "To address this unique tumor specificity, we herein examined the effects of IDH1 R132C, which is the most prevalent mutant in cartilaginous tumors, on the differentiation properties of human mesenchymal stem cells (hMSCs)." (PMID 26161668, 2015). "Patients with IDH1-R132H positive tumours however were significantly younger (44.0 vs. 54.0; p = 0.038)." (PMID 25849605, 2015). "Although several markers of tumor proliferation and metabolism have been identified in GBM and are used clinically (EGFRvIII amplification, MGMT promoter methylation, IDH1 mutation status), prognostic markers of invasive capacity are largely lacking." (PMID 25714433, 2015). "The frequency of mutations identified at a higher frequency in our study (IDH1, CIC and FUBP1) are similar to those reported by others for this tumor type." (PMID 25694352, 2015). "Mutations of IDH1 and IDH2 as well as those in SDH have been observed in numerous cancers and found to cause global epigenetic changes in the tumor." (PMID 26680454, 2015). "Disease progression in IDH1/2 mutant-bearing tumours is likely to depend on additional contributing genetic events." (PMID 25432631, 2015). "First, we found that patients with IDH1-R132H positive tumours and a volume of CE greater than 5 cm3 were more likely to die within the first 12 months compared to patients with IDH1-R132H positive tumours and less CE." (PMID 25849605, 2015). "84% of grade III tumours and 17% of grade IV had IDH1 or IDH2 mutations that conferred a better prognosis in both; MGMT methylation (defined as average value across 16 CpGs ≥ 10%) occurred in 75% of tumours and was also associated with improved survival." (PMID 24952577, 2014). "Targets were selected based on the reported frequency of hypermethylation in IDH1 (R132H) primary tissue and engineered cell systems as well as their known functional impact in tumoriogenesis or tumor maintenance." (PMID 24077805, 2013). "G-CIMP was also shown to be highly dependent on a mutation in IDH1 or IDH2; 99% of the tumours with a G-CIMP possessed a mutation in either of these genes and none of the tumours without a mutation was G-CIMP positive." (PMID 22771539, 2013). "These paired samples were examined for changes in phenotype, chromosomal deletions, IDH1 mutation, IDH2 mutation and methylation status of tumor-related gene promoters." (PMID 23826216, 2013). "Mutations of IDH1 and IDH2 in combination with microenvironmental effects in certain tumor types are likely the driver mutations that are responsible for the malignant phenotype, rather than simply epiphenomena." (PMID 23847760, 2013).
tumor (continued). "Given the relatively poor prognosis of 4q12 amplified cases in comparison with the IDH1/Proneural tumours, it is possible that these cases represent a distinct clinicopathological subgroup of these GBM." (PMID 23990986, 2013). "Exome sequencing confirmed the IDH1 mutation and revealed novel mutations in FUBP1 and CIC in the primary tumor as well as the xenograft relative to the normal patient genome." (PMID 23527265, 2013). "In line with previous observations we detected similar levels of α-KG in all tumor samples, both IDH1-mutant and -wt." (PMID 24252742, 2013). "All IDH1 mutant tumors were non contrast enhancing and most were located in the frontal lobe (11/14, 79%) with larger tumor size." (PMID 24202336, 2013). "In summary we show that in IDH1-mutant xenografts D-2HG levels are approximately 100-fold higher as compared to normal brain tissue and that these high levels are restricted to the tumor area." (PMID 24252742, 2013). "As both IDH1 and IDH2 mutations result in the generation of the putative oncometabolite, d-2HG, this oncometabolite can be measured directly in tumor samples and serum." (PMID 23847760, 2013). "Our results indicate that transient low doses of decitabine increases expression of genes associated with glial-astrocytic differentiation and induces differentiation in patient-derived IDH1-mutant tumor spheres." (PMID 24077826, 2013). "In a recent report, the staining pattern of IDH1-R132H by clone H09 mAb in enchondroma of Ollier disease is heterogeneous, and the percentage of tumor cells positive for mutant IDH1 ranges from 50% to 90%, indicating intraneoplastic mosaicism." (PMID 24403254, 2013). "The absence of these HIF1α-regulated hypoxia markers is in accordance with recent studies that show an inhibition of HIF1α expression induced by D-2HG and EGLN in IDH1-mutant tumor cells." (PMID 24252742, 2013). "E478 tumor extracts contained highly elevated levels of D-2HG (34.5 nmol/mg protein vs < 0.2 nmol/mg protein in IDH1-wt E434 xenografts; n = 3, p < 0.0001)." (PMID 24252742, 2013). "To investigate the effects of IDH1 and IDH2 mutations on the CS methylome, we conducted genome-wide DNA methylation (DNAm) profiling of 44 central CS tumour samples using the Illumina Infinium 450 K BeadChips12." (PMID 23863747, 2013). "Of these, 92 tumors (95%) representing 44 tumor pairs (94%) revealed an identical IDH1- status in their primary and recurrent tumors." (PMID 22844452, 2012). "The most frequent IDH1 mutant protein (R132H) can be identified by a specific antibody using immunohistochemistry, facilitating precise localization of tumor cells." (PMID 22298889, 2012). "The three to four cores per tumor on the microarrays included between 4 and 51 vessel profiles (mean 18 vessel profiles per tumor), all of which were closely examined for mutant IDH1 protein similar to that seen in the surrounding infiltrating tumor cells." (PMID 22298889, 2012).
tumor (continued). "Other than gliomas, mutations in IDH1 haveonly been reported in Acute Myelogenous Leukemia (AML), suggesting a potential role in tumor initiation." (PMID 21317451, 2010). "A recent study has shown IDH1 appears to function as a tumor suppressor contributes to tumorigenesis in part through induction of the HIF-1 pathway." (PMID 20459648, 2010). "We found ΔT to be significantly different between IDH1‐mutant and ‐wild‐type tumours: While IDH1‐wild‐type tumours have T values similar to those of brain (∼3% difference on average), IDH1‐mutant tumours see elevated T values compared with brain (∼29% difference on average)." (PMID 41436375, 2026). "The tumour T values for the two groups over time implies that tumour T values in IDH1‐mutant mice increase with time, while the trend of tumour values for IDH1‐wild‐type mice is less clear." (PMID 41436375, 2026). "However, the week‐wise breakdown of ΔT depicts opposite trends between IDH1‐mutant and ‐wild‐type mice over the course of tumour development." (PMID 41436375, 2026). "IDH2-mutations were associated with significantly worse DSS compared to IDH-wild-type or IDH1-mutated tumors, independent of tumor grade." (PMID 41906217, 2026). "Targeted drugs, such as FGFR2 inhibitors and IDH1 inhibitors, block tumour cell proliferation and signalling pathways, thus increasing the effectiveness of immunotherapy and restoring the ability of the immune system to recognize tumours." (PMID 40861435, 2025). "In a clinical setting, this could be problematic because missing an IDH1-mutant tumor might result in suboptimal treatment strategies." (PMID 40299088, 2025). "Notably, IDH1 R132Q-expressing U87MG tumor xenografts had significantly increased transcripts of many integrins as described, as well as EGFR and MDM2 compared to R132H." (PMID 40188944, 2025). "Furthermore, the average H2O2 concentration was measured at 68.54 ± 4.51 μm in IDH1‐WT GL261 tumor and 109.3 ± 9.44 μm in IDH1‐MUT GL261 tumors." (PMID 40171868, 2025). "In our study, Major Axis Length (MajAL) and Surface Area were highly informative features for IDH1 classification, reflecting differences in tumor geometry that may correlate with infiltrative tumor growth and aggressiveness." (PMID 40299088, 2025). "Our investigation revealed that soft tumor parenchyma correlated with wild-type IDH1 expression, and a highly malignant blood flow architecture was seen in all IDH1 wild-type gliomas, but IDH mutant gliomas exhibited a comparatively benign blood flow architecture." (PMID 40944023, 2025). "An important long-term goal would be a comparison of the methylation and transcription profiles of tumor models of less common but physiologically relevant IDH1 mutants, especially those we and others have shown to have distinct D2HG levels and kinetic profiles." (PMID 40188944, 2025). "Regardless of histological grade, SMI-based tumor vascular architecture proved to be an effective predictor of IDH1 mutation status." (PMID 40944023, 2025). "This may explain why IDH1 mutations are highly prevalent in many CNS malignancies like GBM and could play an important role in tumor progression." (PMID 41450919, 2025). "If increased catalytic rates conferred among some IDH1 mutants can indeed lead to higher D2HG concentrations in tumor models, understanding the impact of these mutations on tumor growth rates, epigenetic, and transcriptomic profiles can ultimately help us better predict patient prognosis." (PMID 40188944, 2025). "The results revealed that WSCD2 protein expression was strongly related to gender (χ2 = 4.820, p = 0.028) and tumor grade (χ2 = 12.837, p = 0.002) but not linked to age, histological classification, IDH1-R132H mutation status, and GFAP expression." (PMID 38415455, 2025).